APOC1P1 (apolipoprotein C1 pseudogene 1)
Synonyms: lincRNA-APOC1P1-3; ApoC-IA; APOC1P
Gene: Transcribed unprocessed pseudogene on chromosome 19 (44,926,976 to 44,931,058, forward strand). Ensembl gene ENSG00000214855.
Diseases named in the same sentence as APOC1P1 in open-access papers:
APOC1P1 is named in the same sentence as 16 diseases in open-access papers, as found by Europe PMC text mining. Sharing a sentence is not in itself a finding about the gene and the disease. The quoted sentences say what the papers report.
breast carcinoma (8 papers, 2016 to 2023). "The animal experiment also demonstrated that the lncRNA APOC1P1-3 promotes lung metastasis of breast cancer cells (MDA-MB-231)." (PMID 33902604, 2021). "In summary, lncRNA APOC1P1-3 can promote the anoikis resistance of breast cancer cells and specifically bind to miRNA-188-3p acting as a “sponge” to block the Bcl-2 inhibition." (PMID 33902604, 2021). "Our study supports a theory that lncRNA APOC1P1-3 can promote development of breast cancer metastasis via anoikis resistance by specifically binding to miRNA-188-3p to block the inhibition of Bcl-2." (PMID 33902604, 2021). "In a previous study, we found lncRNA APOC1P1-3 to be aberrantly overexpressed in breast cancer, and correlated with the tumor size and hypomethylation in its promoter." (PMID 33902604, 2021). "We previously showed that long non-coding RNAs APOC1P1-3 (lncRNA APOC1P1-3) inhibit apoptosis of breast cancer cells." (PMID 33902604, 2021). "In our previous studies, we sought out long intergenic non-coding RNA APOC1P1-3 from breast cancer tissues and cell lines." (PMID 33902604, 2021). "Previously, we measured and compared lncRNA APOC1P1-3 expression in breast cancer and its adjacent tissues via microarray chip." (PMID 33902604, 2021). "LncRNA APOC1P1 was found overexpressed in breast cancer, and its upregulation promotes cell proliferation." (PMID 31871500, 2019). "We found that APOC1P1-3 repressed apoptosis of breast cancer to facilitate its proliferation through altering the apoptotic protein levels." (PMID 27228351, 2016). "A study indicated that lncRNA APOC1P1-3 could promote breast cancer metastasis by specifically binding miRNA-188-3p to block Bcl-2 inhibition through anoikis-resistance." (PMID 38049825, 2023). "The results support that the lncRNA APOC1P1-3 could promote anoikis resistance of breast cancer cells." (PMID 33902604, 2021). "Previously, we found lncRNA APOC1P1-3 is related to breast cancer." (PMID 33902604, 2021). "It is reported that LncRNA APOC1P1 is overexpressed in breast cancer." (PMID 31871500, 2019). "For example, APOC1P1 could directly bind to tubulin to decrease α-tubulin acetylation, to inactivate caspase-3, and to inhibit apoptosis in breast cancer." (PMID 30305026, 2018). "In present studies, we tested the hypothesis that APOC1P1-3 overexpression involved in breast cancer progression." (PMID 27228351, 2016). "In present studies, we identified aberrantly expressed long intergenic non-coding RNA APOC1P1-3 (lincRNA-APOC1P1-3) in breast cancer by microarray, verified it by quantitative real-time PCR, and assessed methylation status in the promoter region by pyrosequencing." (PMID 27228351, 2016). "LncRNA APOC1P1-3 inhibits apoptosis by decreasing α-tubulin acetylation in breast cancer." (PMID 28033431, 2016). "On the basis of these findings, we propose a regulatory mechanism for APOC1P1-3 in breast cancer." (PMID 27228351, 2016). "This study demonstrates that overexpression of APOC1P1-3 can inhibit breast cancer apoptosis." (PMID 27228351, 2016). "We analyzed the expression of lncRNA APOC1P1-3 in one normal (MCF-10A), three malignant (T47D, MCF-7, MDA-MB-231) breast cell lines, and 24 breast cancer tissues by real-time qPCR." (PMID 33902604, 2021). "For example, lncRNA APOC1P1–3 has been found to inhibit breast cancer cell apoptosis by decreasing α-tubulin acetylation; lncRNA NORAD has been reported to suppress breast cancer metastasis by sequestering S100P." (PMID 32943090, 2020). "LncRNA apolipoprotein C-1 pseudogene 1 (LncRNA APOC1P1), which is located at 19q13.2 between APOC-I and APOC-IV, was shown to inhibit apoptosis by decreasing α-tubulin acetylation in breast cancer." (PMID 31871500, 2019).
cholangiocarcinoma (1 paper, 2018). A carcinoma that arises from the intrahepatic biliary tree (intrahepatic cholangiocarcinoma) or from the junction, or adjacent to the junction, of the right and left hepatic ducts (hilar cholangiocarcinoma). "Diagnostic value of lncRNAs for Cholangiocarcinoma: HULC(b), H19(c), LPAL2(d), C3P1(e), AC005550.3(f), APOC1P1(g), PVT1(h),and sensitivity: Sen." (PMID 30305026, 2018).
coronary artery disease (1 paper, 2018). "rs6756513 is associated with platelet count and it had an edQTL in an intron of C3P1. rs10847434 is associated with coronary artery disease and had an edQTL with an editing site in the most 3′ exon of APOC1P1 in liver." (PMID 29527417, 2018).
fatty liver disease (1 paper, 2018). A reversible condition wherein large vacuoles of triglyceride fat accumulate in liver cells via the process of steatosis. "The negative correlation may indicate a regulatory function of APOC1P1. rs1883350 is associated with fatty liver disease and we identified one liver edQTL slightly downstream of PNPLA3 (Patatin-like phospholipase domain-containing protein 3)." (PMID 29527417, 2018).
nephrotic syndrome (1 paper, 2023). A collection of symptoms that include severe edema, proteinuria, and hypoalbuminemia; it is indicative of renal dysfunction. "Group 1 was characterized by major risk genes for developing LOAD (APOC1 and APOC1P1) and immune-related genes (RELB and CBLC), whereas group 2 was characterized by genes associated with kidney disorders, such as nephrotic syndrome (AXDND1, FBP1, and MIR2278)." (PMID 37386009, 2023).
tumor (4 papers, 2016 to 2021). "We found that APOC1P1-3 expression was positively associated with tumor size (P=0.0142)." (PMID 27228351, 2016).
cancer (3 papers, 2016 to 2022). A tumor composed of atypical neoplastic, often pleomorphic cells that invade other tissues. "Previous evidence shows that long noncoding RNA (LncRNA) APOC1P1 plays an important role in cancer development." (PMID 31871500, 2019). "Clearly, further researches about the expression and function of LncRNA APOC1P1 in cancer initiation and progression are warranted." (PMID 31871500, 2019). "In order to further explore the potential mechanism of the five key genes (APOC1, APOC1P1, ISYNA1, C7orf61 and APOE) and whether these genes functioned through common cancer pathways, we analyzed them using the GSCALite platform by pathway activity module." (PMID 35371313, 2022). "To investigate the role of APOC1P1-3, we compared its expression profiles in cultured cells (MCF10A versus BT549, MCF7, MDA-MB-231, MDA-MB-453, MDA-MB-468, MCF7/Adr, and T47D) and 25 pairs fresh tissues (cancer versus matched normal tissues) with qPCR." (PMID 27228351, 2016).
APOC1P1 also shares sentences with these, for which no sentence is quoted: Alzheimer disease (1 paper); angina pectoris (1); atherosclerotic heart disease (1); Clear Cell Renal Cell Carcinoma (1); delirium (1); dementia (1); diabetes (1); Hypertension (1); kidney disorder (1).